NF1 (neurofibromin 1)
Diseases named in the same sentence as NF1 in open-access papers (continued):
Sharing a sentence is not in itself a finding about the gene and the disease.
Malignant pheochromocytoma (3 papers, 2017 to 2024). "In conclusion, we report a rare case of NF1‐associated malignant pheochromocytoma with bone metastasis." (PMID 38966763, 2024).
mammary adenocarcinomas (3 papers, 2014 to 2024). "All of these indels model “Nf1 deficiency” and induce highly penetrant, aggressive ER+/PR + mammary adenocarcinomas in female rats." (PMID 38799507, 2024). "By creating indels in the CSRD of one copy of the Nf1 gene, each of these Nf1-deficient immunocompetent rat lines developed highly penetrant, aggressive mammary adenocarcinomas with varying times on tumor onset." (PMID 38799507, 2024). "Phenotype penetrance and expression extended through second generation breeding including mammary adenocarcinomas in both Nf1-deficient males and females." (PMID 30182054, 2018). "Additionally, Nf1 deficiency correlated with increased estrogen receptor phosphorylation in mammary adenocarcinomas." (PMID 30182054, 2018). "The resulting Nf1 indels induced highly penetrant, aggressive mammary adenocarcinomas that express estrogen receptor (ER) and progesterone receptor (PR)." (PMID 30182054, 2018). "The genomically-characterized mammary adenocarcinomas from these mice displayed deletions of certain genes, and the NF1 gene was deleted in the vast majority of the mouse mammary adenocarcinomas." (PMID 25051360, 2014). "Moreover, Nf1 animals often developed mammary adenocarcinomas with mixed histology such as acinar and solid; cystic, papillary, ductal, and solid; and cystic, acinar, and solid." (PMID 30182054, 2018). "In addition, we observed mixed histopathology in the mammary adenocarcinomas from male Nf1 rats." (PMID 30182054, 2018).
memory impairment (3 papers, 2023). "Finally, and taking into account prior knowledge that the Nf1+/− mouse model presented memory impairment, we explored the sex differences in spatial memory of these animals." (PMID 37101298, 2023).
metastatic colorectal cancer (3 papers, 2018 to 2023). "Recently, SMAD4 and NF1 mutations were reported as potential biomarkers for poor prognosis to cetuximab-based therapy in metastatic colorectal cancer patients." (PMID 34205170, 2021).
microcephaly (3 papers, 2016 to 2023). A congenital or acquired developmental disorder in which the circumference of the head is smaller than normal for the person's age and sex. "NF1 is also linked to the regulation of the GTPase pathway, which plays a role in ectoderm differentiation and is linked to microcephaly, structural brain abnormalities, and intellectual disability." (PMID 34108589, 2021).
ovarian mucinous carcinoma (3 papers, 2024 to 2025). "WGS analyses revealed rearrangements involving PTEN, NF1, and NF2 in ovarian endometrioid carcinomas and NF1 and MED1 in ovarian mucinous carcinomas." (PMID 40981433, 2025). "Whole-genome sequencing revealed rearrangements involving PTEN, NF1, and NF2 in ovarian endometrioid carcinomas and NF1 and MED1 in ovarian mucinous carcinomas." (PMID 40981433, 2025).
pancreatitis (3 papers, 2020 to 2025). Inflammation of the pancreas. "In this particular case, the combination of factors associated with pancreatitis (pancreas divisum and the genetic change in CFTR) and the pathogenic variant in NF1 may have had a synergistic role to increase the risk for occurrence of multiple tumors." (PMID 32425982, 2020).
papillary thyroid carcinoma (3 papers, 2017 to 2024). "We present a case of a 39-year-old woman with NF1 who was diagnosed initially with papillary thyroid carcinoma (PTC) and subsequently presented with a painful breast lump." (PMID 32399324, 2020).
papilloma (3 papers, 2018 to 2025). A benign epithelial neoplasm that projects above the surrounding epithelial surface and consists of villous or arborescent outgrowths of fibrovascular stroma. "Histological examination by H&E confirmed that most tumors from the Nf1+/+ mice progressed to differentiated SCC, whereas all tumors from Nf1+/− mice maintained their typical papilloma architecture." (PMID 30479396, 2018). "In the context of NF1, patients are by definition heterozygous for the NF1 gene due to inactivation of one copy of NF1 in all their somatic cells, but these patients rarely develop papillomas or SCC." (PMID 30479396, 2018). "To determine the influence of an Nf1+/− microenvironment on the progression from papillomas to SCC, we further aged the mice that developed papillomas from both genotypes (Nf1+/+ and Nf1+/−) for an additional period of 23 weeks." (PMID 30479396, 2018). "This indicated that an Nf1+/− microenvironment repressed the progression from the benign papilloma to SCC." (PMID 30479396, 2018). "Eventually, some Nf1+/+ mice developed papilloma but to a much lesser extent (12%, 6 out of 50; Fischer exact test value = 0.036)." (PMID 30479396, 2018). "In a two-step 7,12-dimethylbenz[a]anthracene/12-O-tetradecanoylphorbol-13-acetate (DMBA/TPA) skin carcinogenesis model, the Nf1+/- microenvironment exhibited dueling roles by accelerating benign papilloma formation, while antagonizing malignant transformation to squamous cell carcinoma." (PMID 38473354, 2024). "This indicates that an Nf1+/− microenvironment accelerate papilloma formation." (PMID 30479396, 2018). "Strikingly, in the following months after TPA treatment, the gross morphology of all the papillomas evaluated from the Nf1+/− mouse model did not progress further and remained benign." (PMID 30479396, 2018).
Pectus excavatum (3 papers, 2021 to 2025). A defect of the chest wall characterized by a depression of the sternum, giving the chest ("pectus") a caved-in ("excavatum") appearance. "The association of NF1 with anterior chest wall deformities has been recently reported, especially the pectus excavatum (PE)." (PMID 40225171, 2023). "Aside from NSLFP and pectus excavatum, our study did not identify a distinct phenotype compared to ‘classic’ NF1, aligning with a previous detailed series of 22 NF-NS patients and contrasting with other studies focusing on specific NF1 patients with NF1 PVs or associated CHM." (PMID 40289159, 2025).
perineurioma (3 papers, 2022 to 2025). A usually benign perineurioma not associated with a nerve, arising from the soft tissues. "Intraneural perineuriomas harbor missense mutations in TRAF7, whereas soft tissue perineuriomas commonly show deletions of chromosome 22q (NF2) and deletions of chromosome 17q11 (NF1), as well as chromosome 2p deletions or rearrangements or deletions of chromosome 10q (sclerosing variant)." (PMID 37046591, 2023).
pulmonary valve stenosis (3 papers, 2019 to 2020). The pathologic narrowing of the orifice of the pulmonary valve. "Three patients had pulmonary valve stenosis (PVS) and one patient with a frameshift variant in the NF1 gene had hypertrophic cardiomyopathy, rare features of NF1 and LS but common in NSDs." (PMID 32107864, 2020). "Present data confirm the significant frequency of CHD in patients with NF1, and provide further evidence for a higher than expected prevalence of NF1 in-frame variants and NS-like characteristics in NF1 patients with CHD, particularly with pulmonary valve stenosis." (PMID 31487937, 2019). "Similarly, patients with non-truncating NF1 mutations displayed two- and six-fold higher risk of developing CHD (odds ratio = 1.9713, 95% confidence interval (CI): 1.1162–3.4814, p = 0.0193) and pulmonary valve stenosis (odds ratio = 6.8411, 95% CI: 2.6574–17.6114, p = 0.0001), respectively." (PMID 31487937, 2019).
renal cell carcinoma (3 papers, 2016 to 2025). "No patients had NF1-associated complications, but one case had developed three malignancies not known to be directly related to NF1; renal cell carcinoma, mixed thyroid carcinoma and lentigo maligna." (PMID 33853649, 2021).
Renal cyst (3 papers, 2019 to 2022). A fluid filled sac in the kidney. "The family history revealed the existence of cysts in several relatives (eyelid cysts in III-7, head cysts in III-8, and renal cysts in III-10), but no formal diagnosis of NF1 was made in any of them." (PMID 31443423, 2019).
skin abnormalities (3 papers, 2021 to 2026). "NF-1 is an autosomal dominant genetic disorder with an incidence of 1/3,000-1/4,000, characterized by diverse manifestations including skin abnormalities, neurological tumors, and musculoskeletal abnormalities." (PMID 41788354, 2026).
skin nodule (3 papers, 2010 to 2021). "Because this disease is highly associated with NF1 or MEN2b, screening for associated clinical features such as external stigmata, skin nodule, multiple café-au-lait spots, and tumors at other sites such as breast, uterus, thyroid and colon, are recommended." (PMID 31277169, 2019). "The patient presented with classic clinical features of NF-1, which was confirmed by pathologic evaluation of an excised skin nodule." (PMID 20219130, 2010).
soft tissue tumors (3 papers, 2013 to 2023). "The latest WHO classification of bone and soft tissue tumors (5th edition) clearly defines MPNST occurring in NF1 as intermediate between a benign and malignant tumor." (PMID 39516973, 2023).
superficial spreading melanoma (3 papers, 2021 to 2025). A type of melanoma that typically occurs in light-skinned individuals ranging in age from young adults to the elderly. "In turn, BRAF mutations are the dominating genetic causative factor in superficial spreading melanoma (SSM), whereas for ALM, typical mutations can be found in the BRAF, NRAS, KIT, and NF1 genes." (PMID 34575876, 2021).
T-cell acute lymphoblastic leukemia (3 papers, 2021 to 2025). Acute lymphoblastic leukemia of T-cell origin. "Although NF1 splice mutations are often mistaken for silent mutations by sequencing methods, evidence that synonymous mutations of the NF1 gene are selected in cancers such as T-cell acute lymphoblastic leukemia signals a need for more research in this area." (PMID 33957863, 2021). "In addition, the co-deletion of RASA1 and NF1 results in the development of T-cell acute lymphoblastic leukemia." (PMID 38874808, 2024).
thymoma (3 papers, 2018 to 2023). A neoplasm arising from the epithelial cells of the thymus. "As previously discussed, this pathway might be activated by chromosome 19q CNV (mainly in thymomas) or by a mutation in PTEN, PIK3CA, or NF1 (in both thymomas and thymic carcinomas)." (PMID 36836670, 2023). "For patients with types A and B1/B2 thymoma (n = 9), seven gene mutations, including MTOR, BRCA1, APC, NF1, HRAS, NTRK3, and PTCH1, were detected, and each gene appeared only once in patients with non-TCs+type B3 TETs." (PMID 34307137, 2021).
Turner syndrome (3 papers, 2022 to 2025). Turner syndrome is a chromosomal disorder associated with the complete or partial absence of an X chromosome. "Neurofibromatosis type 1 (NF-1) is a multisystemic genetic disorder that is only rarely observed in association with Turner syndrome." (PMID 35463623, 2022). "It has been massively reported that connective tissue disorders such as MFS, LDS, NF-1 and Turner syndrome are strongly associated with acute aortic dissection." (PMID 35414028, 2022). "Only six cases of Turner syndrome associated with NF-1 have been reported in the literature." (PMID 35463623, 2022).
urothelial carcinoma (3 papers, 2017 to 2022). A malignant neoplasm derived from the transitional epithelium of the urinary tract (urinary bladder, ureter, urethra, or renal pelvis). "Integrated analysis of 131 urothelial carcinomas showed recurrent mutations in 32 genes, with 14% of tumours having NF1 mutations." (PMID 28637487, 2017). "The urothelial carcinomas harbored three private mutations with specific annotation, two KRAS mutations (p.Gly13Asp and p.Ala146Thr) with resistance level R1, and the level 4 NF1 p.Arg2637Ter." (PMID 35260767, 2022).
uterine corpus endometrial carcinoma (3 papers, 2018 to 2024). A endometrial carcinoma (disease) that involves the body of uterus. "On the other hand, TCGA somatic samples carrying both NF1 and SDC2 mutations are scarce (N = 14/10,437), most of them (57.1%) also related to uterine corpus endometrial carcinomas." (PMID 32858845, 2020). "Detection of NF1-inactivating events was also improved in COAD, OV, and uterine corpus endometrial carcinoma (UCEC), as compared to NF1-specific classifiers." (PMID 29617658, 2018).
vascular malformation (3 papers, 2021 to 2025). A non-neoplastic disorder that is the result of defects of vascular morphogenesis. "Although they both had the same mutation at the same locus of NF1, the patient had seizures, whereas the patient’s mother did not have seizures and presented with the more common fibromatosis complications of intracranial tumors and vascular malformations." (PMID 40703627, 2025). "This case indicates that minor injuries such as acupuncture-related ones could cause severe hemorrhage in patients with vascular malformation related to NF1." (PMID 38022201, 2023). "NF-1 is a rare, autosomal dominant disease, which is strongly related with vascular malformations and whose first symptoms commonly appear in childhood." (PMID 33395412, 2021).
viral infection (3 papers, 2006 to 2023). "To test the role of the E1A-HD2 fusion protein during viral infection, we inserted the E1A-HD2 gene into an oncolytic adenovirus (serotype 5) with Tcf-binding sites in the E1A, E1B, E2 and E4 promoters and deletion of the NF1, NFκB and AP1 sites in the E3 promoter." (PMID 17020613, 2006).
Visual impairment (3 papers, 2020 to 2025). "In this analysis, we limited our analysis to females, since Nf1-OPG-induced visual impairment is sexually dimorphic in mice." (PMID 41497446, 2025). "Firstly, our data suggest a correlation between the sex and visual impairment in patients below 21 years of age with NF1-OPG as females were more likely to have visual impairment than their male counterparts in our cohort." (PMID 34809690, 2021). "Neuropsychological outcomes displayed a high degree of heterogeneity and complex relationships with visual impairment and NF1 co-diagnosis." (PMID 32094393, 2020).
vitamin D deficiency (3 papers, 2020 to 2022). A nutritional condition produced by a deficiency of VITAMIN D in the diet, insufficient production of vitamin D in the skin, inadequate absorption of vitamin D from the diet, or abnormal conversion of vitamin D to its bioactive metabolites. "We provide an exhaustive and detailed analysis of the most relevant preclinical and clinical studies aimed at analyzing the correlation between vitamin D deficiency and NF1 lesion progression." (PMID 33066259, 2020).
acoustic neuroma (2 papers, 2021 to 2023). A type of benign brain tumor that begins in the Schwann cells, which produce the myelin that protects the acoustic nerve - the nerve of hearing. "Moreover, due to the Swedish ICD-coding system, we could only distinguish NF1 from NF2 based on the absence of benign meningioma or acoustic neuroma diagnoses." (PMID 37490289, 2023).
adrenal adenoma (2 papers, 2015 to 2022). "Biallelic inactivation of NF1 had been previously reported in one case of adrenal cortical tumor, and adrenal adenoma have been described in association with NF1 in several reports." (PMID 25775093, 2015). "Our data suggest that previously observed adrenal adenoma cases in NF1 were not coincidental, and might have been caused by the biallelic inactivation of NF1 in the adrenal cortex." (PMID 25775093, 2015).
albinism (2 papers, 2023 to 2024). A congenital disorder characterized by partial or complete absence of melanin pigment in the eyes, hair, or skin. "With this aim in mind, we can cite a French and a Korean team that have recently developed guidelines to help practitioners in the diagnosis and care of albinism and NF1." (PMID 36823650, 2023).
autoimmune thyroid disease (2 papers, 2017 to 2021). Inflammatory disease of the thyroid gland due to autoimmune responses leading to lymphocytic infiltration of the gland. "Nanda at al. described the case of a 6-year-old boy diagnosed as having NF1 associated with AA and autoimmune thyroiditis." (PMID 33557156, 2021). "In this study, we determined thyroid function and autoimmune thyroid diseases in patients with NF1 to identify the possible association between NF1 and thyroid disease." (PMID 28552839, 2017). "Autoimmune thyroiditis (AT) is rarely seen in association with NF1." (PMID 28552839, 2017). "This is the first report that has searched for autoimmune thyroid diseases in patients with NF1." (PMID 28552839, 2017). "Graves’ disease is another autoimmune thyroid disease that occurs in patients with NF1." (PMID 28552839, 2017).
benign peripheral nerve sheath tumor (2 papers, 2023 to 2025). "MRI is crucial for the preoperative diagnosis of MPNSTs, with several key characteristics that can aid in differentiating MPNST from benign peripheral nerve sheath tumors such as NF1." (PMID 40182390, 2025). "Therefore, among the various benign peripheral nerve sheath tumors in NF-1 patients, the diagnosis of MPNST is crucial." (PMID 38013269, 2023).
blue nevus (2 papers, 2016 to 2025). An intradermal nevus characterized by the presence of benign pigmented dendritic spindle-shaped melanocytes. "This suggested that haploinsufficiency of NF1 could play a role in the progression of blue nevus–type lesions." (PMID 39804140, 2025).
bone tumor (2 papers, 2022 to 2024). "In this study, it was found that about 34% of Chinese bone tumor patients harbored actionable targeted mutations, including CDKN2A, PTEN, FGFR1/2/3, NF1, and NTRK1/2/3." (PMID 35756627, 2022).
Brugada syndrome (2 papers, 2019). A genetically heterogeneous condition characterized by complete or incomplete right bundle branch block accompanied by ST elevation in leads V1-V3. "In addition to NF1, he also suffered from Brugada syndrome (MIM#601144), inherited from his father." (PMID 31443423, 2019).
cerebellar tumors (2 papers, 2005 to 2023). "However, cerebellar tumors produced by genetically engineered mice (GEM), in which biallelic physical (glial progenitor cell) Nf1 inactivation is paired with monoallelic germline Nf1 gene inactivation, do not entirely capture the neuropathological features of the human condition." (PMID 37675821, 2023).
cerebral aneurysm (2 papers, 2020 to 2023). "Therefore, as it is denoted in our patient individuals with both PKD2 and NF1 mutations seemed not have a greater risk for tumor and/or cerebral aneurysm formation than expected with either condition alone." (PMID 32533764, 2020).
cherubism (2 papers, 2014 to 2024). Cherubism is a rare, self-limiting, fibro-osseous, genetic disease of childhood and adolescence characterized by varying degrees of progressive bilateral enlargement of the mandible and/or maxilla, with clinical repercussions in severe cases. "This is the first described patient with coexistence of NF1 and cherubism." (PMID 38281202, 2024).
congenital megacolon (2 papers, 2014 to 2025). "In a pedigree with both NF1 and congenital megacolon, only members with both the paternally derived GDNF R93W allele and maternally inherited NF1 mutation had megacolon." (PMID 25329635, 2014).